IL22 (interleukin 22)
Diseases named in the same sentence as IL22 in open-access papers (continued):
Sharing a sentence is not in itself a finding about the gene and the disease.
tumor (continued). "IL-22 is excessively expressed in human HCC tumor-infiltrated leukocytes (TILs) compared to peripheral lymphocytes." (PMID 24623532, 2014). "Yet, other cytokines secreted by Th17 cells (IL-17F, IL-21, and IL-22) exhibit anti-angiogenic properties, convoluting the overall correlation between Th17 cell activity and tumor growth in the context of angiogenesis." (PMID 24987392, 2014). "On the contrary, IL-22 has been shown to mediate tumor reduction in certain models of breast cancer." (PMID 24987392, 2014). "IL-22-producing tumor-infiltrating lymphocytes (TILs) promote tumor growth and metastasis in a mouse model when co-transplanted with tumor cells." (PMID 26344346, 2013). "To investigate the effect of IL-22 on tumor growth and metastasis, we designed an in vivo tumorigenesis assay using the subcutaneous cell transplantation model." (PMID 23379788, 2013). "In this study we demonstrated that excessive IL-22 in the CC and UC microenvironment leads to tumor growth, inhibition of apoptosis, and promotion of metastasis depend on STAT3 activation." (PMID 23379788, 2013). "In this study, we transplanted this IL-22 related tumor microenvironment beneath the skin of nude mice." (PMID 23379788, 2013). "Our findings of increased gene expression of IL-22 and its related family of cytokines in tumor tissue, as well as increased protein expression of IL-22, IL-22R, and the downstream modulator pSTAT-3, all reinforce the importance of the IL-22 pathway in TSCCs." (PMID 23667456, 2013). "Tumor tissue was analyzed by IHC with IL-22 staining, it exhibited that IL-22 expressing TILs isolated from two patients have proliferated underneath the mice skin (Figure 4C1, C2)." (PMID 23379788, 2013). "Our results show TSCCs, are more proliferative, exhibit a distinct T cell mediated response favoring tumor growth and T cell polarization that favors production of IL-22, and show more diffuse expression of IL-22R." (PMID 23667456, 2013). "TILs exhibiting various IL-22 expression levels isolated from CC patients were demonstrated to enhance tumor growth and metastasis co-transplanted with Hct-116 cells underwent subcutaneous transplantation in mice model." (PMID 23379788, 2013). "In general, we found that the entire family of IL-10 cytokines including IL-10, IL-19, IL-20, IL-22 and IL-24 was increased in tumor compared to normal skin." (PMID 23667456, 2013). "Our results demonstrated significant upregulation of IL-22 in human CC tumor infiltrated leukocytes (TILs) compared to peripheral lymphocytes." (PMID 23379788, 2013). "In contrast, IL-22 producing T cells (Th22 or Tc22) can support keratinocyte proliferation and potentially accelerate tumor growth." (PMID 23667456, 2013). "Though there were only a few reports on the role of IL-22 in tumors, the literature generally supported the tumor-promoting function of this cytokine." (PMID 23316374, 2012). "This is also consistent with the proven impact of IL-22 overexpression in vivo in promoting tumor growth." (PMID 23181064, 2012). "The tumor promoting effect of IL-22 is believed to be mediated by signal transducer and activator of transcription factor 3 (STAT3), an oncogenic transcription factor constitutively activated in various malignancies." (PMID 23316374, 2012). "The purpose of this study is to assess the inhibitory effects of IL-22 on human RCC cell line A498 and to investigate the possible mechanisms underlying the anti-tumor effects of this cytokine." (PMID 21625390, 2011). "In the present study, we investigated the effects of IL-22 on human RCC cell line A498 cells in vitro and in vivo and studied the possible mechanisms underlying the anti-tumor effects of this cytokine." (PMID 21625390, 2011). "Due to the controversial biological effects of IL-22 in tumor cells, it is necessary to carry out further research on this topic." (PMID 21625390, 2011).
tumor (continued). "In contrast, in breast cancer cells, IL-22 was found to effectively reduce the growth of tumor cells, correlated with an inhibition on ERK and AKT phosphorylation and induction of cell cycle arrest." (PMID 21897855, 2011). "The tumor infiltration leukocytes were rare in both IL-22 treatment tumors and controls probably due to the adoption of athymic BALB/c nu mice as the xenograft host." (PMID 21625390, 2011). "Its prognostic value might be contextually dependent on the tumor microenvironment, as high levels of IL-22 in combination with immunosuppressive macrophages may contribute to a more aggressive course of the disease." (PMID 41752653, 2026). "Consistently, in vivo IL22 knockdown abrogates tumor invasion and metastasis and prolongs survival." (PMID 41614909, 2026). "Conversely, γδ T cells may facilitate tumor angiogenesis and stroma remodeling by secreting cytokines such as IL-17 and IL-22." (PMID 41409300, 2025). "Furthermore, IL-26 is known to induce cells that produce IL-22, potentially reducing the cytotoxic T cell function through the activation of anti-apoptotic proteins, thus fostering tumor growth." (PMID 40452847, 2025). "In contrast, LOCRC patients exhibited an accumulation of Th22 cells with impaired capacity to produce IL-22, which supported a dysregulated immune response that may contribute to chronic inflammation and tumor development." (PMID 41425582, 2025). "Furthermore, using the AOM‐DSS model, myeloid: ILC3 cross‐talk through IL‐1β‐induced stimulation of IL‐22 production was found to promote tumour development." (PMID 40899118, 2025). "Moreover, Th17 cells secrete cytokines such as IL-17A and IL-22, which contribute to tumor proliferation and immunosuppression." (PMID 41209556, 2025). "Targeting IL-22 may offer a promising therapeutic approach for Kras-mutant LC, given its diverse biological effects on tumor cell phenotype." (PMID 40806452, 2025). "IL-22 plays a dual role in tumorigenesis: while short-term IL-22 production helps protect against genotoxic stress, prolonged or uncontrolled IL-22 activity can facilitate tumor progression." (PMID 40806452, 2025). "Moreover, ILC3-derived IL-22 further enhances tumor development in bacteria-driven CRC models, underscoring functional parallels with γδT17 cells in inflammation-driven tumorigenesis." (PMID 40872551, 2025). "Based on this, we postulated that the serum concentrations of IL-21 and IL-22 might vary depending on the tumour’s molecular subtype and histological grade." (PMID 40729006, 2025). "The tumour may affect immune cells and modulate IL-21 and IL-22 secretion independently of natural regulatory mechanisms." (PMID 40729006, 2025). "Additionally, Tosti showed that IL22-induced secretion of CXCL1 promotes anti-tumor neutrophil chemotaxis to the TME in CRC cells." (PMID 40083557, 2025). "In cases of chronic inflammation, the activation of the AhR/IL-22 pathway might result in the unusual growth of intestinal epithelial cells and the development of tumor." (PMID 41019044, 2025). "However, in specific contexts, IL-22 can act protectively, supporting tissue regeneration and limiting tumor progression." (PMID 40362280, 2025). "Notably, increased IL-22RA1 gene copy number and mRNA expression have been observed in primary tumor tissues, suggesting a potential for heightened IL-22 responsiveness in tumor cells." (PMID 40806452, 2025). "IL-22 may enhance the growth and development of the intestine, as well as other tissues and neoplasms, by promoting angiogenesis." (PMID 41019044, 2025). "They then measured the cytotoxic activity of CD8+ T cells and the apoptosis of tumor cells to assess how IL-22+ Th cells might influence the effectiveness of anti-PD-1 therapy." (PMID 39325360, 2025). "On the other hand, TIL-secreted IL-22 prompted CRC to recruit anti-tumor TAN through CXCL2." (PMID 40087771, 2025).
tumor (continued). "For the group, the upregulation of IL-22 could play a role in establishing the tumor microenvironment in mycosis fungoides." (PMID 38607023, 2024). "SCC tissue and proximal healthy tissue also showed different responses to direct CP ex vivo, with higher levels of cytochrome c, higher IL10, TNFα, and IFNγ release, and lower IL22 released from tumour tissue indicating significantly increased stress and apoptosis in malignant tissues." (PMID 38785562, 2024). "Additionally, IL-22 expression was also significantly increased in CRC tissues compared to adjacent non-tumor tissues." (PMID 39073546, 2024). "Additionally, IL‐22, an epithelial growth factor promoting tumor cell proliferation in vitro and closely related to tumor metastasis, is significantly upregulated in lung‐tumor‐associated γδ T cells." (PMID 39429871, 2024). "Collectively, IL-22 may promote tumor cell invasion and metastasis by activating the PI3K/AKT signaling pathway, and inhibition of the PI3K/AKT signaling pathway may reverse the effects of IL-22." (PMID 39073546, 2024). "While, in an AOM/DSS-induced CRC model, deletion of IL-22 increased in tumor number and tumor size." (PMID 38331868, 2024). "Moreover, pro-inflammation cytokines, such as Il1b, Il12b and Il18, were upregulated in the tumor of Il21r−/− mice; whereas anti-inflammation cytokines, including Il10 and Il22 were decreased in the tumor of Il21r−/− mice." (PMID 38720319, 2024). "Therefore, we showed much interest in the relationship between tumor cell-intrinsic IL-22/STAT3 axis and NK cell-meditated killing in sorafenib resistance in HCC." (PMID 38596684, 2024). "Collectively, IL-22 could contribute to sorafenib resistance in HCC by activating STAT3/CD155 signaling axis to decrease the sensitivities of tumor cells to sorafenib-mediated direct cytotoxicity and NK cell-mediated lysis." (PMID 38596684, 2024). "It has been reported that IL-22 could accelerate HCC progression through promoting tumor cell proliferation, migration and invasion, as well as inhibiting apoptosis." (PMID 38596684, 2024). "Briefly, an upregulation of IL-22 in the serum or tumor tissue of HCC patients is common." (PMID 38596684, 2024). "Increased serum levels of IL-22 may reflect the degree of inflammation and production and release of IL-22 by tumor cells." (PMID 39073546, 2024). "The NOG model has revealed the tumor-suppressive role of microRNA-16, while IL-22 may facilitate tumor metastasis." (PMID 38665428, 2024). "However, the regenerative cell survival signaling of IL-22 has the significant potential to shift toward tumor formation when overactivated in an uncontrolled manner." (PMID 39195286, 2024). "In addition, IL-22 significantly impaired sorafenib-mediated antitumor effect in HCC by activating tumor cell-intrinsic STAT3/CD155 axis to inhibit the cellular toxicity of sorafenib and NK cell -mediated killing to HCC cells." (PMID 38596684, 2024). "Combining the analysis of IL-22 expression levels with clinical data, we found that patients with high IL-22 expression presented with larger tumor diameters, more frequent microvascular invasion, and were more likely to be at an advanced stage of the disease (Stage III) at diagnosis." (PMID 38596684, 2024). "Therefore, our findings and the literature evidence suggest that IL-22 plays an essential role in facilitating tumor progression and serve as a promising biomarker in HCC." (PMID 38596684, 2024). "Still, in relation to Th17 cells in CRC in an animal model, when the tumor was induced by azoxymethane with dextran sulfate sodium, TGF-β present in the TME induced the differentiation of IL-22-producing Th17 through the expression of aryl hydrocarbon receptor (AHR) contributing to tumor growth." (PMID 38690280, 2024).
tumor (continued). "It is therefore hypothesized that when IL‐22 lacks correct inhibiting signals in the intestine during a steady state, for instance by IL‐22BP, it may initiate tumor formation by signaling epithelial cells to continuously proliferate." (PMID 38363052, 2024). "Notably, IL4I1 can activate AHR ligands in tumor cells via tryptophan metabolism, which in turn supports IL-22 production in ILCs." (PMID 37160121, 2023). "However, Patients with IBD have a considerably elevated risk of CRC, IL-22 can activate STAT3 in IECs to promote cell proliferation and play a major role in maintaining tumor development." (PMID 37304260, 2023). "IL-22, whilst possessing both pro- and anti-inflammatory effects, can promote cancer cell growth and enhance chemoresistance, allowing infiltration of M2-like macrophages in adipose tissue, and driving a systemic anti-tumour effect." (PMID 36980567, 2023). "Similarly, in the 4T1 mouse model (a model similar to metastatic triple-negative BCs), the level of IL-22 mRNA showed an increase in tumor tissues compared with normal mammary tissues." (PMID 37835465, 2023). "Similarly, in other tissues and carcinomas, IL-22 regulates the proliferative potential of epithelial stem progenitors and tumor cells." (PMID 37726288, 2023). "The reason maybe that IL-22 and IL-17 secreted by colon ILC3s are involved in the occurrence of inflammation and tumor growth." (PMID 37304260, 2023). "Furthermore, in vitro analysis on TNBC cell lines (MDA-MB-231 and MDA-MB-468) also showed that through the activation of STAT3/MAPKs/AKT pathway, IL-22 enhances tumor cell migration and their resistance to paclitaxel chemotherapy in a dose-dependent manner." (PMID 37835465, 2023). "However, during tumor development, IL-22 is highly expressed and the expression of IL-22 binding protein (IL-22BP) is restricted, resulting in excessive production of IL-22 and promoting cancer occurrence." (PMID 37304260, 2023). "NOD-like receptor family pyrin domain containing 3 (NLRP3) inflammasome activation within the tumor microenvironment can induce the activation of IL-1β, which subsequently activates RORγt to promote the secretion of IL-22 by Th17 cells, thereby promoting disease advancement." (PMID 37680632, 2023). "IL-22 is highly expressed in tumor tissue, blood, and malignant pleural effusion in NSCLC." (PMID 36776832, 2023). "The authors postulate that IL-22 may be a novel target in advanced CTCL to inhibit tumor invasion and metastasis." (PMID 37874473, 2023). "CAFs typically secrete CXCL12, TGF-β, LOXL2, HGF, and IL-22 to promote tumor progression." (PMID 36992704, 2023). "However, TGF- β promotes the development of IL-17+IL-22 + T cells, and the produced IL-22 can regulate the tumor niche and promote the occurrence of CAC by activating transcription factor STAT3 to promote the gene expression of core stem cells." (PMID 38273841, 2023). "Persistently upregulated IL-22 can promote inflammation and accelerate tumor growth." (PMID 37908362, 2023). "Notably, CD4 T cells have the ability to produce significant amounts of IL-22 cytokines, which have been implicated in driving HCC progression by promoting tumor cell proliferation." (PMID 38235128, 2023). "Additionally, cancer cells can influence memory CD4 T cells to express and release IL-1 in an IL-22-dependent manner, thereby facilitating tumor growth." (PMID 38235128, 2023). "However, the relationship between IL22RA1 and various types of IL22-producing cells in specific tumor tissues still needs to be confirmed in the future." (PMID 35874683, 2022). "After activating the myeloid differentiation factor 88 (MyD88), the invading commensal bacteria and their products interact with TLRs on tumor-infiltrating myeloid cells, leading to the production of inflammatory cytokines such as IL-23 activating the production of IL-6, IL-22, and IL-17A." (PMID 35565269, 2022).
tumor (continued). "Furthermore, it was reported that the level of IL-22 increases in tumor tissues and the malignant pleural effusion (MPE) of NSCLC hosts." (PMID 35669104, 2022). "In addition, IL-22 was identified to possess anti-tumorigenic traits in different tumor models of colorectal and breast cancer." (PMID 36551508, 2022). "The role of IL-22 in promoting tumor invasion has been confirmed in a variety of cancers." (PMID 35669104, 2022). "Furthermore, RNA sequencing of hepatocytes revealed five genes that were upregulated upon IL-22 stimulation in vitro, many of them known to possess tumor-promoting effects in similar contexts." (PMID 36551508, 2022). "New therapies might include the modification of tumor-promoting or -inhibiting mediators of the immune system, such as interleukin (IL)-22 and its natural antagonist IL-22 binding protein (IL-22BP)." (PMID 36551508, 2022). "Furthermore, the use of IL-22 neutralizing antibodies inhibits tumor growth, angiogenesis, and microvascular density." (PMID 35626056, 2022). "Furthermore, according to previous studies, the speed of scratch-wound repair and the ability of tumor cells to pass through the membrane are facilitated after IL-22 exposure in NSCLC cell lines in a dose-dependent manner." (PMID 35669104, 2022). "IL22 is important for B cell recruitment to tertiary lymphoid structures, and depletion of B cells reduces IL22 production, which can stimulate cell behaviour typical of aggressive tumours." (PMID 35743743, 2022). "Interestingly, cytokines produced by classical pro-tumor immune cells such as Tregs, which produce IL-10 and IL-35; Th17 cells, which produce IL-17 and IL-22; or Th2 cells with IL-4, are all pro-angiogenic factors." (PMID 35626056, 2022). "To further confirm the increased stemness will affect tumor recurrence and metastasis, we analyzed their relations to inflammation, we found a good correlation with pro-inflammatory factors like IL-17, IL-22, and IL-23, which are reported as important factors for tumor initiation." (PMID 36386200, 2022). "We review some beneficial bacteria that act on DCs, NK cells, cytotoxic T cells, and helper T cells to promote the secretion of the pro-tumor cytokines IFN-1, IFN-γ, and IL-2 and down-regulate the secretion of TNF-α, IL-6, IL-10, and IL-22, thus exerting anti-tumor immune effects." (PMID 36438840, 2022). "Moreover, the phosphorylation of p38-MAPK/AKT/STAT3 was enhanced by IL-22 in the tumor samples, and these results were similar to those in vitro." (PMID 35669104, 2022). "NKp46 has been associated with good prognosis in human NSCLC (owing to the formation or maintenance of tertiary lymphoid structures (TLS), release of IL-22, TNF-α, IL-8, and IL-2 and recognition of lung tumour cells and tumour-associated fibroblasts via the NKp44 receptor." (PMID 35406451, 2022). "In addition, signaling pathways, such as MAPK and AKT, are also critical for IL-22 to participate in the regulation of tumor growth." (PMID 35669104, 2022). "Indole and its derivates can promote the expression of anti-inflammatory factor IL-22 to regulate intestinal homeostasis, but in the later stage of cancer, IL-22 may promote tumor progression." (PMID 34966278, 2021). "Moreover, IL-22 has been shown to induce gefitinib resistance both in vitro and in vivo, indicating that IL-22 induction within the tumor microenvironment complicates the acquired EGFR-TKI-resistance in NSCLC." (PMID 33466795, 2021). "Both the proliferative and anti-apoptotic effects on epithelia and other tissues commonly attributed to IL-22 signaling as well as a potential inhibitory effect on T cell responses may lead to a permissive environment for tumor growth." (PMID 33692792, 2021). "In addition, cancer cells induce IL-22 production by memory CD4+T cells via IL-1β in order to promote tumor growth." (PMID 33846436, 2021).